SIRT7 (sirtuin 7)
Diseases named in the same sentence as SIRT7 in open-access papers (continued):
Sharing a sentence is not in itself a finding about the gene and the disease.
lung carcinoma (9 papers, 2019 to 2024). "Restored levels of ARF and decreased expression of tumor-promoting genes after loss of SIRT7 suggested an impact of the SIRT7–NPM–ARF axis on proliferation of lung cancer cells." (PMID 38870055, 2024). "Consistently, inhibition of SIRT7 renders lung cancer cells highly susceptible to the effects of gemcitabine, a widely employed antimetabolite in lung cancer treatment." (PMID 38383727, 2024). "Some studies suggested the carcinogenic potential of SIRT7, whose expression levels were associated with several cancers, including breast, ovarian, and lung cancers, thereby classifying SIRT7 as a carcinogenic gene." (PMID 32528869, 2020). "SIRT7 promotes proliferation and migration of lung cancer cells both in vitro and in vivo by stimulating G1/S cell cycle transition and promoting EMT mainly through activation of the AKT and ERK1/2 signaling cascades." (PMID 38383727, 2024). "We also observed reduced levels of ARF in individual lung cancer cells expressing high levels of SIRT7 and vice versa." (PMID 38870055, 2024). "Pharmacological manipulation of the SIRT7–NPM–p14ARF axis represents an attractive option to target lung cancer cells with an intact and active ARF gene." (PMID 38870055, 2024). "SIRT7 exerts pro-tumorigenic functions also in lung cancer and enhanced SIRT7 levels were found in this malignancy compared with healthy tissues counterparts." (PMID 38383727, 2024). "The data provide evidence that SIRT7 promotes lung cancer progression by destabilizing ARF independently of its catalytic activity both in vitro and in vivo." (PMID 38870055, 2024). "Altogether, we propose a model in which SIRT7 accelerates lung cancer progression by directly interacting with ARF, preventing the association of ARF with NPM, thus causing ARF ubiquitination and proteasomal-dependent degradation." (PMID 38870055, 2024). "Essentially, SIRT7 abolishes the capacity of ARF to suppress expression of genes required for proliferation of lung cancer cells, thereby facilitating tumorigenesis." (PMID 38870055, 2024). "SIRT7–p14ARF complex formation was corroborated by coimmunoprecipitation of endogenous proteins in H1299 lung cancer cells." (PMID 38870055, 2024). "ARF protein stability was analyzed in lung cancer cell lines, in which SIRT7 and NPM expression was supressed, either alone or in combination, following treatment with CHX." (PMID 38870055, 2024). "Mechanistically, SIRT7 prevents association of ARF to Nucleophosmin and thereby facilitates ARF proteasomal-dependent degradation in lung cancer cells." (PMID 38870055, 2024). "As expected, IF analysis demonstrated that both SIRT7 and p14ARF localize in the nucleolus in lung cancer cell lines, allowing interactions of the two molecules in this organelle." (PMID 38870055, 2024). "Depletion of ARF in SIRT7-deficient cells prevented this phenotype, providing evidence that SIRT7 depletion retards proliferation of lung cancer cells in an ARF-dependent manner." (PMID 38870055, 2024). "Consistent with the observation that SIRT7 destabilizes ARF regardless of its catalytic activity, expression of either wild-type or catalytically inactive SIRT7 into SIRT7 knockout lung cancer cells increased expression of genes repressed by ARF." (PMID 38870055, 2024). "The same downregulation of CCNE1 was also apparent in SIRT7 KD ARF-positive Calu-3 lung cancer cells and importantly in lungs of SIRT7-mutant mice, demonstrating the physiological relevance of this phenomenon." (PMID 38870055, 2024). "It acts as a potent oncogene in numerous malignancies, but the molecular mechanisms employed by SIRT7 to sustain lung cancer progression remain largely uncharacterized." (PMID 38870055, 2024). "Our bioinformatics analyses of transcriptomic data from human lung cancer samples demonstrated that high SIRT7 expression in tumors correlates with increased expression of genes normally repressed by ARF, exclusively in tumors harboring an intact CDKN2A locus." (PMID 39036727, 2024).
lung carcinoma (continued). "We demonstrate that SIRT7 exerts oncogenic functions in lung cancer cells by destabilizing the tumor suppressor alternative reading frame (ARF)." (PMID 38870055, 2024). "Similar results were obtained in both Calu-3 and PC-14 lung cancer cell lines following shRNA-mediated inhibition of SIRT7." (PMID 38870055, 2024). "We observed a significant increase of p14ARF protein levels in H1299 human lung cancer cells, in which SIRT7 expression was suppressed by two independent SIRT7-targeting shRNAs compared to scrambled shRNA controls." (PMID 38870055, 2024). "Taken together, these data strongly suggest that SIRT7 controls expression of critical genes involved in lung cancer progression in an ARF-dependent manner." (PMID 38870055, 2024). "To study the relevance of the SIRT7–ARF axis for lung cancer growth in vivo, we employed a xenograft mouse model." (PMID 38870055, 2024). "Destabilization of ARF by SIRT7 promotes proliferation of lung cancer cells both in vitro and in vivo." (PMID 38870055, 2024). "In another xenograft tumor model established using lung cancer H1975 cells in nude mice, SIRT7-WT and SIRT7-2E overexpression consistently retarded tumor growth and significantly relieved tumor burden compared to the control (EV) and SIRT7-2A." (PMID 34433808, 2021). "SIRT7 also bolsters the survival of lung cancer cells in response to chemotherapy." (PMID 38383727, 2024). "RT-qPCR analysis of ARF expression demonstrated a significant increase in ARF mRNA levels in SIRT7-depleted H1299 cells but not in Calu-3 cells, indicating that SIRT7 not only influences ARF stability but also interferes with gene expression or mRNA stabilization at least in some lung cancer cells." (PMID 38870055, 2024). "Thus, targeting SIRT7 in lung cancer cells offers a prospective strategy to overcome drug resistant cancers." (PMID 38383727, 2024). "Furthermore, SIRT7 represses the expression of pro-apoptotic genes, promoting the survival of lung cancer cells and facilitating tumor growth." (PMID 38383727, 2024). "Remarkably, inhibition of SIRT7 also enhanced the repression of ARF target genes in ARF-positive Calu-3 lung cancer cells further supporting the hypothesis that SIRT7 controls expression of Nectin2, XRCC1, and SUPT5H in an ARF-dependent manner." (PMID 38870055, 2024). "To explore whether SIRT7 requires NPM to interact with ARF, we generated stable NPM KD lung cancer cells overexpressing V5-tagged p14ARF and analyzed binding of exogenous p14ARF with endogenous SIRT7." (PMID 38870055, 2024). "Furthermore, administration of the proteasome inhibitor MG132 restored ARF levels in SIRT7-depleted H1299 lung cancer cells transfected with WT and catalytic inactive mutant SIRT7." (PMID 38870055, 2024). "In accordance with the hypothesis, we observed that SIRT7 overexpression suppressed the growth of xenografted H1975 lung cancer cells, which possess the constitutively activated EGFR L858R/T790M mutation." (PMID 34433808, 2021). "Thus, SIRT7-mediated changes in ARF levels may influence expression of genes involved in lung cancer progression." (PMID 38870055, 2024). "To explore this possibility, we performed RNA-sequencing of H1299 lung cancer cells stably expressing scrambled or ARF-targeting shRNA as well as of H1299 cells expressing V5-tagged SIRT7." (PMID 38870055, 2024). "In fact, it has been reported that SIRT7 interacts with ATM, a key regulator of the NPM–ARF pathway in lung cancer cells." (PMID 38870055, 2024). "Consistent with the dispensability of SIRT7 catalytic activity for inhibition of ARF, we found that expression of either WT or the SIRT7 HY mutant into SIRT7 KO lung cancer cells stimulates proliferation and anchorage-independent growth to a similar extent." (PMID 38870055, 2024). "In sharp contrast, CCNE1 expression did not change or even increased in ARF-negative SIRT7-depleted H226 and H322 lung cancer cells, respectively." (PMID 38870055, 2024).
lung carcinoma (continued). "SIRT7-dependent destabilization of ARF clearly induced expression of critical genes promoting tumor progression that is normally repressed by ARF, thereby stimulating lung cancer cell proliferation." (PMID 38870055, 2024). "Moreover, we found an inverse correlation between SIRT7 mRNA expression and CDKN2A protein levels in human lung cancers." (PMID 38870055, 2024). "The existence of ARF-independent functions of SIRT7 for controlling tumor cells are also supported by a recent report by Zhao and collaborators, who used lung cancer cells that do not express ARF." (PMID 38870055, 2024). "Additionally, bioinformatics analyses revealed an inverse correlation between SIRT7 and ARF protein levels across diverse lung cancer cells." (PMID 38870055, 2024). "Lung cancer-related studies show that SIRT7 is overexpressed in NSCLC and SIRT7 can promote human NSCLC cell growth and metastasis via regulating G1-to-S-phase transition, EMT, and activation of Akt and extracellular signal-regulated kinase 1/2 (ERK1/2) signaling." (PMID 36117172, 2022). "To analyze whether SIRT7 controls ARF protein stability, we monitored p14ARF protein levels at different time points after treatment with the translation inhibitor cycloheximide (CHX) both in H1299 and in Calu-3 lung cancer cell lines." (PMID 38870055, 2024). "Finally, inhibition of SIRT7 catalytic activity by the pan-sirtuin inhibitor nicotinamide (NAM) did not influence the levels of ARF in lung cancer cells." (PMID 38870055, 2024).
ovarian carcinoma (9 papers, 2014 to 2024). A malignant neoplasm originating from the surface ovarian epithelium. "Elevated expression of SIRT7 has been detected in endometrial and ovarian cancer when compared with healthy tissues." (PMID 38383727, 2024). "SIRT7 is highly expressed in ovarian cancer tissues and cells, and silencing SIRT7 can inhibit the proliferation, invasion and migration of ovarian cancer cells." (PMID 37894746, 2023). "It seemed that SIRT6 and SIRT7 displayed both oncogenic and tumor-suppressive properties in ovarian cancer." (PMID 31113446, 2019). "Moreover, inhibition of SIRT7 in endometrial and ovarian cancer cells leads to diminished cell proliferation, migration and higher sensitivity to anti-cancer drugs treatments." (PMID 38383727, 2024). "Finally, in ovarian cancer, SIRT7 restrains the activity of the transcription factor GATA4 to effectively activate the Wnt signaling cascade and stimulate cancer cells growth." (PMID 38383727, 2024). "With respect to SIRT7, it was reported that SIRT7 was unregulated in ovarian cancer cells compared with normal couterparts, and could promote cell growth and colony formation, and reduce cell apoptosis." (PMID 31113446, 2019). "The upregulation of SIRT7 has been shown to induce ovarian cancer cell migration." (PMID 29100388, 2017). "Oncogenic SIRT7 could also suppress GATA4 transcriptional activity and activate the Wnt signaling pathway in ovarian cancer." (PMID 37691108, 2023).
melanoma (7 papers, 2019 to 2025). A malignant, usually aggressive tumor composed of atypical, neoplastic melanocytes. "Under ER stress, SMAD4 expression was significantly up-regulated in melanoma cells with SIRT7 deficiency." (PMID 36918544, 2023). "The suppressive effect of SIRT7 deficiency on melanoma progression was CD8+T cell-dependent, which was partially caused by the reduction of PD-L1 via the IRE1α-XBP1 axis." (PMID 36918544, 2023). "Further co-IP analysis showed that the interaction between K48-linked ubiquitin chain and SMAD4 was impaired in A2058 melanoma cells with SIRT7 deficiency, whereas significantly increased in WM35 melanoma cells after the overexpression of SIRT7." (PMID 36918544, 2023). "Then, we proved that the deficiency of SIRT7 potentiated tumor cell death under stress in vitro and suppressed melanoma growth in vivo." (PMID 36918544, 2023). "In parallel, SIRT7 expression deficiency significantly suppressed melanoma growth in vivo by promoting tumor cell apoptosis." (PMID 36918544, 2023). "To investigate the biological functions of miR-148b and SIRT7 in melanoma cells, we performed gain-of-function and loss-of-function experiments in A375 cells stably transduced with LV-hsa-miR-148b; LV-SIRT7 was transfected to A375 cells." (PMID 33274232, 2020). "Ultimately, we investigated the mechanism underlying SIRT7 up-regulation in melanoma." (PMID 36918544, 2023). "Therefore, CD8+T cells and macrophages were also greatly implicated in tumorous SIRT7-mediated anti-tumor immunity under ER stress in melanoma." (PMID 36918544, 2023). "Moreover, membrane PD-L1 expression was prominently reduced in SIRT7-deficient melanoma cells compared with control under ER stress." (PMID 36918544, 2023). "Besides, we also employed 451Lu melanoma cell line for the verification of the role of SIRT7 in melanoma, and it revealed that SIRT7 deficiency amplified cell death resulted from the treatment with TM or HBSS." (PMID 36918544, 2023). "SIRT7 assumes a pivotal pro-tumorigenic role in melanoma by enhancing various aspects of tumor development including growth, survival, migration and evasion from anti-cancer immune responses." (PMID 38383727, 2024). "SIRT7 appears to stimulate the IRE1α-XBP1 pathway in melanoma cells by deacetylating and destabilizing SMAD4." (PMID 38383727, 2024). "Of note, the mRNA of IRE1α was prominently reduced after the knockdown of SIRT7 in TM-treated melanoma cells, indicating that the regulation of IRE1α by SIRT7 occurred at the transcriptional level." (PMID 36918544, 2023). "Of note, while SIRT7 exerts a marginal impact on tumor cell proliferation, invasion, and migration in melanoma under normal conditions, it displays a prominent protective role in maintaining tumor cell survival under stressful circumstances." (PMID 36918544, 2023). "SIRT7 staining score was significantly higher in melanomas than nevus, and revealed more prominent increase in metastatic melanomas compared to primary ones." (PMID 36918544, 2023). "In line with this, immunohistochemical staining analysis also displayed a positive correlation between SIRT7 expression and p-p65 expression, providing in vivo evidence of the regulatory relationship between NF-κB p65 and SIRT7 in melanoma." (PMID 36918544, 2023). "Herein, we reported that SIRT7 orchestrates melanoma progression by simultaneously promoting tumor cell survival and immune evasion via the activation of unfolded protein response." (PMID 36918544, 2023). "In parallel, the overexpression of SIRT7 in WM35 melanoma cell also induced the activation of ERK, while a marginal impact on JNK or p38 MAPK activation was observed." (PMID 36918544, 2023). "Melanoma cells were pre-transfected with siRNA against SIRT7 and then processed to the treatment with TM (ER stress inducer) or HBSS (nutrient deprivation)." (PMID 36918544, 2023). "Ultimately, it was proved that NF-κB p65 contributed to SIRT7 up-regulation in melanoma under stress." (PMID 36918544, 2023).
melanoma (continued). "There was a robust positive correlation between SIRT7 staining scores and XBP1s staining scores in melanoma tissues." (PMID 36918544, 2023). "Herein, we first identified that SIRT7 was a stress-responsive factor and its expression was significantly increased in melanoma." (PMID 36918544, 2023). "In parallel, overexpression of SIRT7 in WM35 melanoma cell promoted the mRNA levels and secretion of TNFα, IL-8, and VEGFα under ER stress." (PMID 36918544, 2023). "Collectively, these data proved that SIRT7 acted as a cyto-protective factor that enabled melanoma cell survival under either ER stress or nutrient deprivation." (PMID 36918544, 2023). "Then, we proved that the knockdown of SIRT7 exerted marginal effects on melanoma cell proliferation under normal conditions, whereas it potentiated tumor cell death under ER stress." (PMID 36918544, 2023). "The immunohistochemical staining analysis in TMA also revealed that the intensity of SIRT7 was in significantly positive correlation with that of PD-L1, further supporting the regulatory relationship between SIRT7 and PD-L1 in melanoma." (PMID 36918544, 2023). "Taken together, SIRT7 can be employed as a promising target to restrain tumor growth and increase the effect of melanoma immunotherapy." (PMID 36918544, 2023). "Taken together, our data demonstrated that SIRT7 orchestrated melanoma progression by simultaneously promoting tumor cell survival and immune evasion via the selective activation of the IRE1α-XBP1 axis." (PMID 36918544, 2023). "The fluorescence intensity indicating SIRT7 expression was higher in melanoma tissues than in the benign nevi, where the intensity was too weak to detect." (PMID 33274232, 2020). "Overall, miR-148b inhibits the malignant biological behavior of melanoma by reducing the expression level of SIRT7." (PMID 33274232, 2020). "According to the findings of the present study, it was demonstrated that SIRT7 was overexpressed but miR-148b expression level was significantly decreased in melanoma cells and tissues." (PMID 33274232, 2020). "In conclusion, miR-148b inhibits the malignant biological behavior of melanoma by reducing the expression level of SIRT7." (PMID 33274232, 2020). "The expression heat map of the top 50 differentially expressed genes in the 51 primary melanoma and 27 common acquired nevus tissue samples was as shown, and the relative expression of SIRT7 of the two groups was as shown." (PMID 33274232, 2020). "Ectopic expression of miR-148b reduced the proliferation, migration, and invasion of melanoma cells, but SIRT7 reversed these functions of miR-148b." (PMID 33274232, 2020). "It was established that the expression of miR-148b was downregulated in melanoma while that of SIRT7 was upregulated but negatively regulated by miR-148b through binding to the 3′UTR of SIRT7." (PMID 33274232, 2020). "In this study, we demonstrated that miR-148b acts as an antioncogene in melanoma by reducing the expression level of SIRT7." (PMID 33274232, 2020). "In the current study, it was established that downregulation of miR-148b, a novel miRNA for regulating SIRT7 in melanoma, contributed to the increased expression of SIRT7." (PMID 33274232, 2020). "This study investigated the mechanism of miR-148b/SIRT7 on how it affects the malignant biological behavior of melanoma." (PMID 33274232, 2020). "The findings of these experiments suggested that miR-148b acts as a suppressor of the malignant biological behavior of melanoma by inhibiting SIRT7." (PMID 33274232, 2020). "The results of RT-qPCR also indicated that SIRT7 was significantly overexpressed in melanoma tissues compared to benign nevus tissues." (PMID 33274232, 2020). "Isoform antagonism is especially pronounced in the context of melanoma, as SIRT1 associates with chemokine-rich CD8+-high niches and reinforces responses to PD-1 blockade, while SIRT7 triggers the IRE1α–XBP1 stress pathway to upregulate PD-L1 and promote immune evasion." (PMID 41425553, 2025).